HIF1A (hypoxia inducible factor 1 subunit alpha)
Diseases named in the same sentence as HIF1A in open-access papers (continued):
Sharing a sentence is not in itself a finding about the gene and the disease.
breast cancer (continued). "As one of the most important regulators, elevated expression of HIF-1α has been identified in esophageal cancer 7, 9, 10, prostate cancer 11, lung cancer 12, breast cancer 13 and other malignant tumors." (PMID 31892989, 2020). "Together, these studies indicate that vitamin C is a safe therapeutic supplement either independently or through HIF-1α suppression to combat breast cancer metabolism." (PMID 33266219, 2020). "Further analysis showed that HIF-1α mRNA possesses in its 3′ UTR sequence a miR-let-7 response element: let-7 was thus responsible for HIF-1α degradation and low stem-like phenotypes in breast cancer cells." (PMID 33291403, 2020). "In hypoxic breast cancers, CD44s overexpression facilitates tumor proliferation and invasion by enhancing HIF1A signaling." (PMID 33168816, 2020). "Taken together, these data again suggest that HIF1A is preferentially required for the growth of breast cancer-derived CTCs in the brain." (PMID 33298946, 2020). "Together, these findings indicate that HIF1A and its downstream effectors are increased in human breast cancer brain metastases compared with primary breast tumors." (PMID 33298946, 2020). "A strong positive correlation between Nur77 and HIF-1α expression in human breast cancer specimens was also confirmed." (PMID 33245358, 2020). "Considering the distinct function of CLDN6 and HIF-1α in tumour metastasis, we chose a breast cancer cell line with strong invasion, MDA-MB-231, and a breast cancer cell line with weaker invasion, SkBr-3, for the following experiments." (PMID 32093760, 2020). "This HIF-1α-induced effect is vital for induction of the BCSC phenotype in breast cancer when in response to hypoxia or cytotoxic chemotherapy." (PMID 33489906, 2020). "Here, in breast cancer cells, the expression of HIF-1α and Nur77 also increased instantaneously under hypoxic conditions." (PMID 33245358, 2020). "We found that both HIF‐1α (5802 ± 580.7 vs 43682 ± 2039, P < .001) and Kindlin‐2 (899.6 ± 77.39 vs 8018 ± 679.5, P < .001) were highly expressed in breast cancer." (PMID 32436609, 2020). "Consistently, the overexpression of SENP1 or HIF-1α significantly restored the CLDN6-mediated reductions in circulating tumour cells, indicating that CLDN6 inhibits breast cancer metastasis through SENP1/HIF-1α signalling in vivo." (PMID 32093760, 2020). "Iron deficiency leads to overexpression of VEGF and HIF-1α, while iron overload induces activation of the MAPK pathway, resulting in increased breast cancer recurrence and incidence rates, respectively." (PMID 33292585, 2020). "The reduction in SENP1 promotes the SUMOylation of HIF-1α, which decreases the stability and transcriptional activity of HIF-1α, thus contributing to the inhibition of breast cancer metastasis." (PMID 32093760, 2020). "Alternatively, it is also possible that, in our mammary cell mixing experiments, HIF1A-mediated release of growth factors and cytokines from control cells supports mammary tumor growth of cocultured cells with HIF1A knockdown through paracrine mechanisms." (PMID 33298946, 2020). "Breast cancer patients exhibit significantly high HIF-1α levels, which correlate with more aggressive cancer features, and particularly with a poor disease free and overall survival." (PMID 32286485, 2020). "Vorinostat, an HDAC inhibitor suppressing HIF-1α by modulating its translocation, is currently in clinical trials for patients with breast cancer (NCT01720602, NCT03742245, NCT04190056)." (PMID 33266219, 2020). "In this regard, GPER was shown to be involved together with HIF-1α in the cell adaptation to low oxygen tension in diverse tumors as breast cancer." (PMID 32778144, 2020). "Previous studies analyzing CAV1 knockout mice and stroma from breast cancer patients revealed that increased HIF1α target gene expression correlated with reduced CAV1 levels." (PMID 32825247, 2020).
breast cancer (continued). "Collectively, our results demonstrate that the XCL1–XCR1 axis promotes MDA-MB-231 and SK-BR-3 breast cancer cell migration via activation of the ERK/HIF-1α/EMT signaling pathway." (PMID 33374849, 2020). "The miR-373/TBP-2/HIF1α/TWIST signaling axis was related to a poor prognosis of patients with breast cancer." (PMID 32426273, 2020). "It will provide a better understanding of the biological interactions between HIF‐1α, Kindlin‐2, and breast cancer stiffness." (PMID 32436609, 2020). "Cysteine-rich protein 2 (CSRP2), as a novel target of HIF-1α, attributes to breast cancer cell invasion under hypoxic conditions by regulating the formation of invadopodium actin backbone." (PMID 32215176, 2020). "Our study first identified a new mechanism of invasive breast cancer stiffness by linking HIF‐1α and Kindlin‐2 to collagen biogenesis." (PMID 32436609, 2020). "Of note, CSRP2, which is an invadopodia actin-bundling protein that is upregulated by hypoxia (HIF-1α) in various breast cancer cell lines and tumors, is also upregulated in MKL1 ΔN200 cells." (PMID 32699630, 2020). "Our results in MCF-7 breast cancer cells demonstrate that HT decreases HIF-1α protein, probably by downregulating oxidative stress and by inhibiting the PI3K/Akt/mTOR pathway." (PMID 32286485, 2020). "Alternatively, AGR2 was regarded as a binding stabilizer of HIF1α, thereby contributing to the hypoxia-induced doxorubicin resistance in breast cancer." (PMID 32322663, 2020). "knockdown of HIF‐1α leads to reduced migration and invasion of various breast cancer and HIF‐1α also vital maintenance survival and self‐renewal in tumour stem cells and metastasis cancer cell." (PMID 32562470, 2020). "LNT was proven to regulate HIF-1α in order to inhibit the growth of breast tumors, which provides an important reference for the treatment of breast cancer." (PMID 33245358, 2020). "Overexpression of HIF‐1α has been found in a variety of cancers, including pancreatic cancer, breast cancer, prostate cancer, colon cancer and lung cancer." (PMID 32960511, 2020). "While studies insinuate that HIF-1α induces cells to increase their lipid uptake through FABP7 for energy production, more work is required to elucidate the role of HIF-1α in lipid metabolic alteration of breast cancer." (PMID 33266219, 2020). "A Pearson correlation analysis demonstrated that CLDN6 expression was negatively correlated with SENP1 and HIF-1α in breast cancer tissues." (PMID 32093760, 2020). "In normoxia, miRNA-high aggressive breast cancer cell lines show higher HIF-1α expression than miRNA-low poorly metastatic breast cancer cell lines." (PMID 32707933, 2020). "This is the first study that investigates the expression and the prognostic significance of HIF-1α in feline mammary carcinomas." (PMID 32375802, 2020). "Treatment with metformin reportedly caused suppression of tumor angiogenesis by targeting the human epidermal growth factor receptor-2 /hypoxia inducible factor-1 alpha/VEGF (HER2/HIF-1α/VEGF) secretion axis in different breast cancer cell lines." (PMID 31698699, 2019). "Elevated HIF-1α activity was observed in the ALDH+ E CSC population of cultured human breast cancer cells." (PMID 31394796, 2019). "To investigate new therapeutic strategies for treatment-resistant breast cancer, we explored treatment targets using multigene panels, which showed high expression of HIF1A, RAF1, AKT2 and VEGFA in two TNBC cases." (PMID 31018595, 2019). "An interaction between the tumor suppressor breast cancer type 1 susceptibility protein (BRCA1), which possesses ubiquitin E3 ligase activity, and HIF-1α was also found to be important in regulating HIF-1α stability in human breast cancer cells." (PMID 31208103, 2019). "The current study provides an evidence of close association of HIF-1α, MDR1 and LAPTM4B expression with tumor stage, metastasis and chemotherapy treatment in breast cancer patients." (PMID 30746305, 2019).
breast cancer (continued). "HIF-1α-positivity correlated to EGFR-expression in patient breast cancer samples corroborating in vitro data that hypoxia and HIF-activity induce EGFR-expression." (PMID 31821370, 2019). "PANX1 downregulation led to a reduction in the mRNA levels of the hypoxia transcription factor and marker, HIF-1α in breast cancer cells." (PMID 31817827, 2019). "Another miRNA reported targeting HIF-1α is miR-497, thus, it represses the hypoxic conditions and for this reason it is usually downregulated in breast cancer cells." (PMID 31627322, 2019). "Immunohistochemistry was performed to detect the expression of HIF-1α and c-myc protein in breast cancer tissues." (PMID 31577739, 2019). "In breast cancer, negative regulation of HIF-1α by FBP1 results in decreased growth, migration, glucose consumption, and lactate production." (PMID 31552162, 2019). "We showed that Dec1 expression is induced by HIF-1α in oral cancer cells under hypoxia, by TNFα in breast cancer cells under apoptosis, and by TGFβ1/pSmad3 in epithelial–mesenchymal transition of pancreatic cancer cells." (PMID 31597354, 2019). "HIF1A protein is also expressed at high levels in SKBR3 compared with the other breast cancer cell lines, MDA-MB-231 (TNBC) and T47D (HR+/HER2−), under normal culture conditions." (PMID 31018595, 2019). "HIF-1α IHC-signal was exclusively nuclear in control samples of human cells cultured at hypoxic conditions (1% O2) as well as in patient breast cancer samples." (PMID 31821370, 2019). "Intratumoral hypoxia, a common condition in cancer, triggers the expression of HIF-1α which in turn initiates the progression of breast cancer toward metastasis." (PMID 31817810, 2019). "Elsewhere an increase in the level of HIF-1α has been shown to correspond with the pathologic stages of breast cancer." (PMID 30842790, 2019). "Deletion of Hif1a has been reported to markedly impair metastasis in a mouse mammary tumor virus (MMTV) promoter-driven polyoma middle T antigen mouse model of breast cancer." (PMID 30696468, 2019). "HIF1α, a master transcriptional regulator of the response to hypoxia, was upregulated in the mammary tumors of HF offspring (p = 0.048)." (PMID 31889127, 2019). "Numerous studies have indicated a distinct survival advantage associated with reduced expression of HIF-1α, the regulatory subunit of HIF-1, in patients with breast cancer." (PMID 30943919, 2019). "Our previous study demonstrated that hypoxia-induced HIF-1α expression in breast cancer cells involves a cascade of signaling events, including Rac1 activation." (PMID 31462898, 2019). "The positive expression rates of HIF-1α and c-myc protein in breast cancer tissues were 41.4% (36/87) and 55.2% (48/87), respectively." (PMID 31577739, 2019). "A previous study reported that LPA2 of breast cancer cells regulates HIF-1α expression and is involved in cell proliferation, migration, and invasion." (PMID 31035435, 2019). "The increased percentage of HIF-1α-positive tumors formed during adjuvant tamoxifen suggests a role for HIF-1α in escaping tamoxifen’s restraining effects on breast cancer." (PMID 31821370, 2019). "In this study, IHC showed the positive expression rates of HIF-1α and c-myc protein in breast cancer tissues were 41.4% and 55.2%, respectively." (PMID 31577739, 2019). "Previous reports have shown that hypoxia-induced breast cancer cell motility is Rac1 dependent and the Rac1 activity is driven by HIF-1α-mediated transcriptional induction of CXCR4." (PMID 31462898, 2019). "The A2B receptor is hypoxia-responsive and is regulated by HIF-1α in human endothelial cells, intestinal and alveolar epithelial cells, dendritic cells and breast cancer cells." (PMID 31234425, 2019).
breast cancer (continued). "Modulation of glucose‐6‐phosphate dehydrogenase (G6PD)/ Hypoxia inducing factor 1α (HIF‐1α) expression by Nrf2 is therefore involved in the Notch1 pathway‐mediated regulation proliferation, migration, invasion of breast cancer." (PMID 30809937, 2019). "Previously, we reported that in breast cancer, a novel function of KDM8 is its association with PKM2 and its ability to translocate PKM2 into nucleus to become a coactivator of HIF-1α to transcriptionally activate glycolytic genes in favor of Warburg effects." (PMID 30072740, 2019). "In view of this, HIF-1α has become a vital molecular target for breast cancer formation and progression." (PMID 30940798, 2019). "In summary, our findings suggest that Nrf2 contributes to metastatic ability of basal type breast cancer cells through G6PD/HIF‐1α/Notch1 signalling axis." (PMID 30809937, 2019). "Investigations into HIF-1α expression in breast cancers have shown correlation with the expression of HER2, a growth factor receptor overexpressed in 20% of breast cancers and associated with more aggressive disease." (PMID 30670058, 2019). "In pilot study, we found that the expression of HIF-1α significantly increased in breast cancer cell lines and tissue samples with higher malignant behaviors and decreased in luminal subtype breast cancer cells and tissue samples." (PMID 30940798, 2019). "Further study on Nrf2/G6PD/HIF‐1α/Notch1 signalling axis is demanded for realization of basal type breast cancer treatment." (PMID 30809937, 2019). "Previous studies have proposed that glycogen accumulation in breast cancer cells is due to HIF1α mediated increase in GYS1 and/or PPP1R3C expression in hypoxia." (PMID 31536495, 2019). "Previously it has been suggested that elevated HIF-1α expression in breast cancer tissue is an indicator of metastasis and relapse in breast cancer." (PMID 30746305, 2019). "Our results reveal novel function of cardamonin in inhibiting the HIF-1α pathway and its dependent metabolic reprogramming in breast cancer cells." (PMID 31455352, 2019). "In line with the results above, we found that ERα is down-regulated, and HIF-1α levels increased, when ERα-positive breast cancer cells are exposed to hypoxia and HIF-1α accumulate." (PMID 31821370, 2019). "We show here that an increased proportion of tamoxifen-resistant CBCs, i. e. tumors developed during adjuvant tamoxifen treatment, were HIF-1α positive and that HIF-1α-positivity in the tumors led to increased breast cancer mortality (BCM)." (PMID 31821370, 2019). "Second, in order to examine the direct link between miR-181c and HIF-1α dysregulation, miR-181c was stably overexpressed in both breast cancer cell lines." (PMID 31078780, 2019). "Further studies have revealed that C/EBPδ inhibited the expression of FBXW7, thereby increasing the activities of the FBXW7 substrates such as mTOR and HIF-1α and potentiated metastasis in mammary tumors." (PMID 30791487, 2019). "In case of breast cancer, there were 51 patients having high expression of HIF-1α, MDR1 and LAPTM4B while 17 patients were those having low expression of all the three genes." (PMID 30746305, 2019). "As expected, luciferase assay analyses demonstrated that methylation at both non-CpG and CpG loci within the promoter around the TSS can directly silence HIF-1α gene expression in MCF-7 breast cancer cells." (PMID 30940798, 2019). "HIF-1α was undetectable in human breast cancer cells cultured in monolayer at normoxic conditions (21% O2) consistent with the instant degradation of HIF-1α in the presence of oxygen." (PMID 31821370, 2019). "Herein, we report that the hypomethylation at non-CpG and CpG sites in the promoter around its transcription start site (TSS) is an important reason to increase HIF-1α expression in those breast cancer cells or tissue samples with highly malignant behavior." (PMID 30940798, 2019).
breast cancer (continued). "To test this idea, we compared levels of hypoxia-induced HIF-1α accumulation in breast cancer cells following the silencing of NRF2 or the overexpression of miR-181c." (PMID 31078780, 2019). "Suppression of HIF-1α-induced CBR1 by resveratrol (10 μM) increased the sensitivity of hypoxic breast cancer cells to doxorubicin, making the hypoxic cancer cells sensitive to doxorubicin as shown in normoxic cancer cells." (PMID 30791624, 2019). "Clinically, in patients with breast cancer, HIF-1α overexpression identified by immunohistochemistry of tumor biopsies has been associated with increased mortality." (PMID 31505803, 2019). "Overall, the PD and 2‐DG combination inhibits glycolytic metabolism by suppressing HIF1α/HK2 in breast cancer cells." (PMID 30920152, 2019). "All of these metabolic changes are relatively impaired in NRF2-knockdown breast cancer cells, presumably as a result of HIF-1α dysregulation." (PMID 31078780, 2019). "Numerous facts suggest that increased H3K9Ac modification promotes HIF-1α transcription and expression in breast cancer cells." (PMID 30940798, 2019). "Hypoxia induced ORAI3 levels in basal breast cancer cell lines through a pathway involving hypoxia-inducible factor-1 alpha (HIF1α)." (PMID 30754719, 2019). "It has been demonstrated that breast cancer exosome production is increased substantially in hypoxic conditions in a HIF-1α dependent manner." (PMID 31071959, 2019). "Breast cancer cells with miR-181c overexpression exhibited similar behaviors upon hypoxia: HIF-1α accumulation was attenuated and the levels of glycolysis enzymes were suppressed." (PMID 31078780, 2019). "HIF1α was silenced by siRNA in normoxic/hypoxic tumor cells, before RNA sequencing and bioinformatics analyses were performed while using the breast cancer cell line MDA-MB-231 as a model." (PMID 31554283, 2019). "In line with our observation, SET8 is reported to coordinate with HIF1α to modulate glucose metabolism in breast cancer cells." (PMID 30952833, 2019). "Moreover, HIF1-α and hypoxia have been shown to increase the metastatic phenotype in multiple cancer cell types, including in breast cancer in vivo experiments, and have been linked to increased risk of metastasis and mortality in breast cancer patient cohorts." (PMID 31536495, 2019). "Among samples with TNBC, XBP1 and HIF-1α exhibited much higher expressions in samples with highly metastatic breast cancer than those with poor metastasis." (PMID 29416769, 2018). "Chiavarina and colleagues observed that stable HIF-1α overexpression endowed fibroblasts with oncogenic functions, as they increased tumour growth after ectopic co-injection with breast cancer cells." (PMID 29362402, 2018). "In fact, several HIF-1α inhibitors that are in clinical trials (for example, against melanoma, breast cancer and GBM), used in combination with chemotherapy, result in increased tumour responsiveness to treatment and a reduced tumour progression rate." (PMID 30544833, 2018). "Butyrate induced the transcription of SLC16A3, SLC26A3, and HIF1A in sheep ruminal epithelia, human breast cancer, and colon cell lines." (PMID 30258628, 2018). "In agreement with our data, Ece reported a significantly decreased level of HIF1A in patients with type 2 diabetes and breast cancer receiving metformin." (PMID 30217067, 2018). "Autophagy is activated in response to stress (e.g., hypoxic conditions), and HIF1α was shown to be involved in the radiation-induced autophagic cell death in breast cancer cells." (PMID 29688867, 2018). "Inactivation of either HIF-1α or HIF-2α in in vivo breast cancer cell models decreases tumor growth and metastasis to the axillary lymph nodes, lung, and bone." (PMID 29896451, 2018).